ZNF639 (zinc finger protein 639)
Description:
Binds DNA and may function as a transcriptional repressor.
Synonyms: ZASC1; ANC-2H01; ANC_2H01
Tractability: PROTAC: UniProt records ubiquitination sites on it; ubiquitination databases record sites on it.
Gene: Protein-coding gene on chromosome 3 (179,323,031 to 179,338,583, forward strand). Ensembl gene ENSG00000121864.
Subcellular location: Nucleus
Subcellular location (Human Protein Atlas): Nucleoplasm
Gene Ontology:
Molecular function: DNA-binding transcription activator activity, RNA polymerase II-specific; DNA-binding transcription factor activity; protein binding; RNA polymerase II cis-regulatory region sequence-specific DNA binding; transcription cis-regulatory region binding
Biological process: host-mediated activation of viral transcription; host-mediated suppression of viral transcription; negative regulation of DNA-templated transcription; positive regulation of cell growth; positive regulation of transcription by RNA polymerase II; symbiont entry into host cell; regulation of transcription by RNA polymerase II
Cellular component: nucleoplasm; nucleus
Genetic constraint (gnomAD): Loss-of-function variants: 17 observed, 34.73 expected, observed/expected ratio (o/e) 0.49, 90% interval 0.33 to 0.73. The upper end of that interval is the gene's LOEUF score, 0.73, which puts it in group 3 of 6, group 1 being the genes least tolerant of losing a copy. Missense variants: 430 observed, 527.46 expected, observed/expected ratio (o/e) 0.82, 90% interval 0.75 to 0.88. Synonymous variants: 161 observed, 181.55 expected, observed/expected ratio (o/e) 0.89, 90% interval 0.78 to 1.01.
Homologues: Orthologues: macaque ZNF639 (99% identical), chimpanzee ZNF639 (99% identical), pig ZNF639 (99% identical), dog ZNF639 (98% identical), guinea pig ZNF639 (97% identical), mouse Zfp639 (93% identical), rat Zfp639 (93% identical), tropical clawed frog znf639 (57% identical), Drosophila melanogaster CG14442 (6% identical), Drosophila melanogaster CG14440 (4% identical). Paralogues in human: ZNF613 (18% identical), IKZF1 (18% identical), ZNF567 (17% identical), IKZF4 (15% identical), ZNF350 (15% identical), ZNF649 (15% identical), IKZF2 (14% identical), IKZF3 (14% identical), ZNF382 (14% identical), ZNF564 (12% identical), ZNF821 (10% identical).
Diseases named in the same sentence as ZNF639 in open-access papers:
ZNF639 is named in the same sentence as 11 diseases in open-access papers, as found by Europe PMC text mining. Sharing a sentence is not in itself a finding about the gene and the disease. The quoted sentences say what the papers report.
squamous cell carcinoma (1 paper, 2011). A carcinoma arising from squamous epithelial cells. "ZNF639 was originally identified in squamous cell carcinoma as a Kruppel-like transcription factor with mRNA expression levels prognostic for survival and metastasis." (PMID 21226949, 2011).
cancer (5 papers, 2011 to 2022). A tumor composed of atypical neoplastic, often pleomorphic cells that invade other tissues. "The three transcription factors SFPQ, ZNF639 (also known as ZASC1) and PHF20 have been associated with cancer." (PMID 25089626, 2014).
tumor (3 papers, 2006 to 2021). "Three tumor samples (T5, T16, and T19) exhibited high-level amplification in 3q26, including WWTR1, TP63, PIK3CA, SOX2, SOX2-OT, and ZNF639 genes." (PMID 34285259, 2021).
ZNF639 also shares sentences with these, for which no sentence is quoted: infection (3 papers); HIV-1 infection (2); Ataxia (1); endometrial cancer (1); Esophageal Neoplasms (1); Obesity (1); viral disease (1); virus infection (1).